LDHA (lactate dehydrogenase A)
Diseases named in the same sentence as LDHA in open-access papers (continued):
Sharing a sentence is not in itself a finding about the gene and the disease.
cervical cancer (continued). "Additionally, nuclear LDHA has been shown to sense reactive oxygen species, leading to the production of alpha-hydroxybutyrate in human papillomavirus (HPV)-induced cervical cancer." (PMID 35982980, 2022). "LDHA is a glycolysis key enzyme and regulates glycolysis rate, suggesting that lncRNA NEAT1 increases 5-FU resistance via regulation of glycolysis rate in cervical cancer cells." (PMID 36438563, 2022). "Subsequently, expressions of miR-34a and LDHA mRNAs in cervical cancer tissues displayed a remarkably negative correlation." (PMID 33645623, 2021). "Nuclear LDHA gains a noncanonical enzyme activity to produce an antioxidant metabolite, α-HB, which can protect cervical cancer cells from excessive oxidative stress and promote cell growth through epigenetic regulations." (PMID 30356100, 2018). "Ultimately enhancing cervical cancer cell survival, suggesting that targeting LDHA inhibition may not be an optimal therapeutic strategy for cervical cancer." (PMID 41561760, 2025). "We present a molecular mechanism that explains how HR-HPVs promote cervical cancer development through nuclear translocation of LDHA and the product of noncanonical enzyme activity, α-HB, providing a crosstalk between cell metabolism and epigenetic signaling networks." (PMID 30356100, 2018). "Although direct targeting LDHA by miR-34a has been revealed in other cancers, in speaking of lncRNA NEAT1, its function as a ceRNA of miR-34a to further de-suppress LDHA in cervical cancer has not been elucidated." (PMID 33645623, 2021). "Collectively, our findings uncover a non-canonical enzyme activity of nuclear LDHA to epigenetically control cellular redox balance and cell proliferation facilitating HPV-induced cervical cancer development." (PMID 30356100, 2018).
ovarian carcinoma (33 papers, 2014 to 2025). A malignant neoplasm originating from the surface ovarian epithelium. "This study reveals that EMSY and β-catenin cooperatively regulate LDHA expression, with 10–15% of ovarian cancers harboring β-catenin mutations." (PMID 41023769, 2025). "Studies indicate that isoprolactone reduces glucose uptake and lactate production in cisplatin-resistant ovarian cancer cells by targeting LDHA inhibition, increasing the susceptibility of cisplatin, suppressing tumor growth and overcoming resistance." (PMID 41561760, 2025). "In the present study, we evaluated the levels of expression of four selected glycolytic targets (GLUT1, HKII, PKM2 and LDHA) in a large series of ovarian cancers to investigate possible associations with histological subtype and stage of disease." (PMID 29866066, 2018). "Expression of GLUT1, HKII, PKM2, LDHA were analysed by quantitative immunofluorescence in a tissue microarray (TMA) analysis of 380 ovarian cancers and associations with clinicopathological features were sought." (PMID 29866066, 2018). "The higher the levels of LDHA expression are in ovarian cancer cells, the more resistant these cells are to the chemotherapy drug cisplatin." (PMID 41422325, 2025). "In ovarian cancer, lactate dehydrogenase A (LDHA) and other metabolic enzymes contribute to lactate accumulation, which supports chemotherapy resistance and disease progression." (PMID 41422325, 2025). "The studies demonstrated that OVCA429 and OVCA433 cells, cells with ovarian cancer, had lower levels of LDHA mRNA and protein when EMSY expression was knocked down." (PMID 41023769, 2025). "In ovarian cancer, transcription levels of critical enzymes in glycolysis particularly LDHA and pyruvate kinase M show significant positive correlations with RAD23A." (PMID 41561760, 2025). "It was discovered that overexpressing LDHA in ovarian cancer reverses the inhibitory impacts of miR-383." (PMID 40868085, 2025). "CSC components play a pivotal role in the recurrence of ovarian cancer, with lactic dehydrogenase A (LDHA) or aldehyde dehydrogenase (ALDH) emerging as prominent research areas as independent markers for ovarian CSCs." (PMID 38577616, 2024). "The miR-383 was negatively correlated with LDHA in ovarian cancer tissues and it was determined to suppress LDHA by directly targeting the 3′-UTR of LDHA gene." (PMID 37110218, 2023). "Overexpression of LDHA was determined to reverse the inhibitory effect of miR-383 in ovarian cancer." (PMID 37110218, 2023). "In ovarian cancer cell lines, B7-H3 knockout resulted in a decreased level of glycolysis and reduced the expression of lactate dehydrogenase A (LDHA), phosphoglycerate kinase 1 (PGK1) and HIF-1α, which suggests that B7-H3 promotes glycolysis." (PMID 36284349, 2022). "Here, we showed that FOXK1 inhibits cellular senescence and promotes glycolysis and chemoresistance in ovarian cancer through regulating cell senescence- and glycolysis-associated proteins, such as P16, hTERT, HK2 and LDHA." (PMID 32550913, 2020). "CT inhibited the expression of glycolysis-related proteins including glucose transporter 1 (GLUT1), hexokinase 2 (HK2), and lactate dehydrogenase A (LDHA) in ovarian cancer Hey cells and xenograft nude mice by repressing STAT3/SIRT3/HIF-1α signaling pathway." (PMID 32265690, 2020). "MiR-383 functioned as an inhibitor on the proliferation of ovarian cancer cell by targeting LDHA and suppressing the glycolysis." (PMID 31989041, 2019). "This study sought to investigate the variation of expression of molecular components (GLUT1, HKII, PKM2, LDHA) of the glycolytic pathway in ovarian cancers and the effectiveness of targeting this pathway in ovarian cancer cell lines with inhibitors." (PMID 29866066, 2018). "However, the regulatory mechanisms and functions of LDHA in ovarian cancer remain poorly understood." (PMID 41023769, 2025).
ovarian carcinoma (continued). "This study showed ovarian cancer cells overexpressing EMSY produce more lactate and have upregulated LDHA expression; the promoting effect of EMSY on the malignant phenotype of these cells is eliminated when LDHA expression is knocked down or glycolysis is inhibited in ovarian cancer cells." (PMID 41023769, 2025). "Importantly, expression validation in ovarian cancer models revealed consistent overexpression of LDHA and key downstream regulators in cisplatin-resistant phenotypes." (PMID 41422325, 2025). "In conclusion, this study shows that EMSY plays a metabolic regulatory role in ovarian cancer cells, indicating that LDHA could be a therapy target for ovarian malignancies that have EMSY amplification." (PMID 41023769, 2025). "To investigate whether EMSY’s oncogenic role in ovarian cancer relies on its regulation of LDHA, we performed LDHA knockdown in EMSY-overexpressing OVCA429 cells." (PMID 41023769, 2025). "Xiang also discovered that LDHA positivity could diminish the therapeutic efficacy of Olaparib in certain subtypes of ovarian cancer, suggesting LDHA may serve as a molecular target for combating resistance." (PMID 38577616, 2024). "LDHA was upregulated in ovarian cancer tissues when compared to normal ovarian tissues." (PMID 37110218, 2023). "LDHA is a HIF1α-targeted glycolytic gene, which is upregulated in ovarian cancer cells." (PMID 35498135, 2022). "LDHA upregulation has been reported in ovarian cancers when compared to normal tissues." (PMID 29866066, 2018). "Because ovarian cancer overexpresses important enzymes, such as pyruvate kinase M2 (PKM2), hexokinase 2 (HK2), and lactate dehydrogenase A (LDHA), there is an increase in glycolytic activity." (PMID 41023769, 2025). "Aurora-A kinase induced a metabolic shift towards glycolysis and altered the expression of glucose metabolic genes such as LDHA and HK2 by participating and influencing the SOX8/FOXK1 signaling axis in ovarian cancer." (PMID 37110218, 2023). "Han RL reported that miR‐383 suppressed the expression level of LDHA, an mRNA highly correlated with PGK1, by directly binding to its 3'‐untranslated region and thus silenced aerobic glycolysis in ovarian cancer cells." (PMID 34668665, 2021). "Reverse phase protein array analysis identified significant dysregulation of metabolites (LDHA, GAPDH, and TCA intermediates) in ovarian cancer cells after Grb2 downregulation." (PMID 32754300, 2020). "We also compared the expression levels of STAT3, SITR3, HIF‐1α, GLUT1, LDHA, and HK2 of 44 ovarian cancer patient serums with 35 normal controls." (PMID 30094960, 2018). "We tested the expression levels of STAT3, SITR3, HIF‐1α, GLUT1, LDHA, and HK2 in 38 ovarian cancer patient tissues and 22 normal tissues." (PMID 30094960, 2018). "Silencing of HSulf-1 expression in ovarian cancer cells increases glucose uptake and lactate production by upregulating GLUT1 and glycolytic enzymes HK II and LDHA." (PMID 26918353, 2016). "PTTG knockdown in ovarian cancer cells results in the downregulation of c-Myc and several crucial proteins involved in aerobic glycolysis, including PKM2, LDHA, and GLUT1." (PMID 26918353, 2016). "Furthermore, in ovarian cancer tissues, we observed upregulated expression of both EMSY and LDHA in tumor tissues, and the expression of LDHA positively correlated with that of EMSY." (PMID 41023769, 2025). "In terms of mRNAs, one study based on Gene Expression Omnibus (GEO) and The Cancer Genome Atlas (TCGA) databases demonstrates the positive correlations between ovarian cancer biomarkers (such as CD44) and glycolytic biomarkers (such as hexokinase 2 (HK2), lactate dehydrogenase A (LDHA), and ENO1)." (PMID 35498135, 2022). "Mean AQUA expression values for GLUT1, LDHA, HKII and PKM2 in 380 ovarian cancer samples." (PMID 29866066, 2018).
ovarian carcinoma (continued). "Adaptation of the ovarian cancer cells to aerobic glycolysis is supported by the increased expression of the glycolytic enzymes pyruvate kinase isoform M2 (PKM2), hexokinase II, and lactate dehydrogenase A (LDHA)." (PMID 30231564, 2018). "We observed increased LDHA protein expression in both cell lines after 24 h of treatment, suggesting a direct effect of NT1014 on glucose metabolism and enhanced activity of the glycolytic pathway in the ovarian cancer cells." (PMID 27655410, 2016). "The results show that an increase in PTTG levels is accompanied with an increase in LDHA, PKM2, and GLUT-1 expression, illustrating that PTTG may be involved in aerobic glycolysis in ovarian cancer." (PMID 26516926, 2015). "Moreover, we assessed the malignancy markers, including LDHA, CA125, and Ki67 in ovarian cancer." (PMID 37940999, 2023). "For instance, U-box E3 ligase CHIP reduces aerobic glycolysis by ubiquitylating and degrading PKM2 in ovarian carcinoma (OV) cells, while CTLH ubiquitylates PKM2 and lactate dehydrogenase A (LDHA) in a non-degradative pathway, thereby inhibiting glycolysis." (PMID 36276075, 2022). "Although many works report altered expression of glycolysis-related proteins (glucose transporter 1, GLUT1; hexokinase 2, HK2; lactate dehydrogenase A, LDHA) in ovarian cancer, our analysis did not reveal differences in the glucose levels between the studied groups of the samples." (PMID 39456684, 2024).
Sepsis (31 papers, 2016 to 2026). Sepsis is defined as life-threatening organ dysfunction caused by a dysregulated host response to infection. "PMN transcriptomics identified HIF-1α as the LDHA-associated signaling pathway in neutrophils during sepsis." (PMID 35090526, 2022). "Growth differentiation factor 15 (GDF15) protects against sepsis-induced ALI by suppressing the HIF-1α/LDHA glycolytic axis in pulmonary ECs, thereby reducing cytokine production and leukocyte recruitment." (PMID 41488672, 2025). "The results revealed a significant up-regulation of MCEMP1, CD177, and LDHA in the sepsis groups compared to the healthy groups (P < .05)." (PMID 39029061, 2024). "We employed machine learning methods (LASSO, RF, and SVM-RFE) to select 3 diagnostic genes (CD177, LDHA, and MCEMP1) to investigate potential sepsis biomarkers." (PMID 39029061, 2024). "Machine learning algorithms identify 3 diagnostic genes - CD177, LDHA, and MCEMP1 - consistently highly expressed in sepsis patients." (PMID 39029061, 2024). "LDHA, a catalyst in lactate synthesis, is upregulated in numerous pathologies, such as tumors, liver fibrosis, pulmonary fibrosis, sepsis, and hypertension." (PMID 39683818, 2024). "Suberoylanilide hydroxamic acid (SAHA) increases LDHA acetylation, reducing its activity and glycolysis rate and alleviating sepsis." (PMID 39683818, 2024). "Lactate dehydrogenase A (LDHA) downregulation can improve immune function in sepsis by inhibiting glycolysis in polymorphonuclear neutrophils contributing to neutrophil immunosuppression." (PMID 39262873, 2024). "In our previous study, upregulation of the glycolytic pathway was observed in primary neutrophils from patients with sepsis, and a regulatory role of LDHA-dependent glycolysis on neutrophil functions was identified." (PMID 37131151, 2023). "Studies show that inhibition of LDHA effectively regulates the NF-κB activation induced by LPS, indicating the potential role of LDHA in sepsis." (PMID 37407986, 2023). "Overall, our study provides insights into the mechanism underlying SAHA’s therapeutic effects in sepsis treatment and highlights LDHA as a potential target for developing novel sepsis treatment." (PMID 37569823, 2023). "The glycolysis-encoding genes HK2 (hexokinase-2), HK3 (hexokinase-3), LDHA, and PKM (pyruvate kinase M) in the PMNs of patients with sepsis were significantly altered compared to those in the PMNs of healthy volunteers." (PMID 35090526, 2022). "Both genes were upregulated in patients with SRS1 and each shows evidence of cis-eQTL in sepsis, together with 11 other genes in the network including lactate dehydrogenase A (LDHA)." (PMID 26917434, 2016). "Furthermore, OLFM4 regulates the pro-inflammatory response of lung epithelial cells in sepsis-related ARDS through LDHA-mediated activation of the NF-κB signaling pathway." (PMID 41507134, 2026). "In a mouse model of sepsis, inhibition of LDHA expression by regulating PI3K/Akt-HIF-1α pathway could inhibit glycolysis and contribute to immunosuppression of neutrophils." (PMID 40420943, 2025). "LDHA is phosphorylated and activated, promoting NF-κB signaling through increased ROS production in a positive feedback loop that sustains inflammation in sepsis-induced ARDS lung epithelial cells." (PMID 41488672, 2025). "However, no clinical trials have been conducted to evaluate the safety, tolerance, and efficacy of LDHA inhibitors in sepsis/septic shock." (PMID 39372401, 2024). "Given that lactate is ubiquitously produced by nearly all cells, suppressing LDHA could lead to unpredictable and potentially adverse effects in sepsis." (PMID 39372401, 2024). "Celastrol, a natural anti-inflammatory compound, binds to LDHA and mitigates sepsis-induced damage." (PMID 39683818, 2024). "In summary, CD177, LDHA and MCEMP1 were identified as diagnostic biomarkers for sepsis." (PMID 39029061, 2024). "Altogether, this highlights the need for therapeutic interventions targeting LDHA in sepsis." (PMID 39468303, 2024).
Sepsis (continued). "Our present study indicated for the first time that HIF-1α may regulate neutrophil functions in sepsis via LDHA." (PMID 35090526, 2022). "Studies analyzing synovial fluid displayed that OA patients have elevated levels of lactic acid in the absence of sepsis, further supporting the notion that LDHA is likely a pathogenic player in human OA70, which we confirmed using human OA tissue samples." (PMID 32647171, 2020). "Our previous experiments suggested that targeting LDHA or P300 can inhibit the lactylation of ENO1 in ECs, thereby improving survival in a mouse model of sepsis." (PMID 41532698, 2026). "During the hyperinflammatory phase of sepsis, HIF-1 activates lactate dehydrogenase A (LDHA), increasing lactate production and glycolytic flux." (PMID 41562069, 2025). "CD38high C1 monocytes of the Sepsis group highly expressed oxidative stress related genes and glycolysis signature related genes, such as ENO1, PKM, PGK1, and LDHA, which were key glycolytic enzymes." (PMID 40145840, 2025). "First of all, the Warburg phenotype in activated immune cells is a generally accepted phenomenon in sepsis, mediated via increased activity of PKM2 and LDHA." (PMID 39468303, 2024). "It has been demonstrated that inhibiting glycolysis contributes to neutrophil immunosuppression during sepsis, regulated by the PI3K/Akt-HIF-1α-pathway-mediated downregulation of lactate dehydrogenase A (LDHA)." (PMID 38001795, 2023). "For example, LDHA downregulation mediated by the PI3K/Akt-HIF-1α pathway results in glycolytic inhibition, which leads to neutrophil immunosuppression during sepsis." (PMID 37728418, 2023). "Drugs that target glycolytic enzymes, such as hexokinase 2 (HK2) or lactate dehydrogenase A (LDHA), are being explored as cancer therapies and could also be tested in sepsis." (PMID 40563999, 2025). "LDHA is responsible for the conversion of pyruvate to lactate and NAD+, while LDHB is responsible for the conversion of lactate to pyruvate and promotes oxidative metabolism, which suggests that hyperlactemia is an independent predictor of Sepsis death." (PMID 40774030, 2025). "Interestingly, the authorsfound high expression of LDHA and low expression of LDHB in patients with Sepsis." (PMID 40774030, 2025). "The authorsfound high expression of LDHA and low expression of LDHB in Sepsis patients." (PMID 40774030, 2025). "Previous studies have shown that inhibiting the expression of lactate dehydrogenase A (LDHA) by regulating the PI3K/Akt-HIF-1α pathway could suppress glycolysis and contribute to immune suppression of neutrophils during sepsis." (PMID 40420943, 2025). "Previous study reported that inhibition of glycolysis leads to neutrophil immunosuppression during sepsis and may be controlled by downregulation of LDHA (lactate dehydrogenase A) mediated by the PI3K/Akt signaling pathway." (PMID 39712033, 2024). "In keeping with our previous work identifying upregulated glycolytic genes including PKM2 and LDHA in LPS-activated primary human neutrophils, increased protein levels of PKM2 in peripheral neutrophils from patients with sepsis and LPS-stimulated dHL-60 cells was observed." (PMID 37131151, 2023). "Our study demonstrated that the inhibition of glycolysis contributed to neutrophil immunosuppression during sepsis and might be controlled by PI3K/Akt-HIF-1α pathway-mediated LDHA downregulation." (PMID 35090526, 2022). "The inhibition of glycolysis contributed to neutrophil immunosuppression during sepsis and might be controlled by PI3K/Akt-HIF-1α pathway-mediated LDHA downregulation." (PMID 35090526, 2022). "Moreover, changes in the expression levels of pyruvate dehydrogenase kinase 1(PDK1), glucose transporter 1(GLUT1), LDHA, and pyruvate kinase M2 (PKM2) regulate macrophage glycolysis, the release of proinflammatory cytokines, and macrophage activation during sepsis." (PMID 35090526, 2022).